RPS4Y1 (ribosomal protein S4 Y-linked 1)
Synonyms: RPS4Y; MGC5070; MGC119100; S4
Tractability: Small molecule: an approved drug acts on it; a structure with a bound ligand is known; a high-quality ligand is known. PROTAC: ubiquitination databases record sites on it; its protein half-life has been measured; a small molecule that binds it is known. Other modalities: a drug acting on it is in phase 2 or 3 trials.
Gene: Protein-coding gene on chromosome Y (2,841,602 to 2,932,000, forward strand). Ensembl gene ENSG00000129824.
Pathways (Reactome):
Metabolism of proteins: Eukaryotic Translation Termination; Formation of a pool of free 40S subunits; Formation of the ternary complex, and subsequently, the 43S complex; GTP hydrolysis and joining of the 60S ribosomal subunit; L13a-mediated translational silencing of Ceruloplasmin expression; PELO:HBS1L and ABCE1 dissociate a ribosome on a non-stop mRNA; Peptide chain elongation; Ribosomal scanning and start codon recognition; SRP-dependent cotranslational protein targeting to membrane; Translation initiation complex formation; ZNF598 and the Ribosome-associated Quality Trigger (RQT) complex dissociate a ribosome stalled on a no-go mRNA
Disease: SARS-CoV-1 modulates host translation machinery; SARS-CoV-2 modulates host translation machinery; Viral mRNA Translation
Metabolism of RNA: Major pathway of rRNA processing in the nucleolus and cytosol; Nonsense Mediated Decay (NMD) enhanced by the Exon Junction Complex (EJC); Nonsense Mediated Decay (NMD) independent of the Exon Junction Complex (EJC)
Cellular responses to stimuli: Response of EIF2AK4 (GCN2) to amino acid deficiency
Developmental Biology: Regulation of expression of SLITs and ROBOs
Metabolism: Selenocysteine synthesis
Gene Ontology:
Molecular function: structural constituent of ribosome; RNA binding
Biological process: translation
Cellular component: membrane; nucleus; ribosome; cytosol; cytosolic small ribosomal subunit; nucleoplasm
Homologues: Orthologues: chimpanzee RPS4Y1 (99% identical), macaque RPS4Y1 (97% identical), tropical clawed frog rps4x (94% identical), zebrafish rps4x (88% identical), Drosophila melanogaster RpS4 (73% identical), Caenorhabditis elegans rps-4 (62% identical). Paralogues in human: RPS4Y2 (94% identical), RPS4X (93% identical).
Diseases named in the same sentence as RPS4Y1 in open-access papers:
RPS4Y1 is named in the same sentence as 30 diseases in open-access papers, as found by Europe PMC text mining. Sharing a sentence is not in itself a finding about the gene and the disease. The quoted sentences say what the papers report.
heart failure (4 papers, 2018 to 2023). Inability of the heart to pump blood at an adequate rate to meet tissue metabolic requirements. "In samples collected from male patients with new-onset heart failure, the RPS4Y1 was overexpression." (PMID 37474895, 2023). "An expression profiling study based on new-onset heart failures caused by idiopathic dilated cardiomyopathy demonstrated that USP9Y, DDX3Y, RPS4Y1, and EIF1AY were significantly upregulated in male patients with high-fold changes." (PMID 29361784, 2018). "In accordance with adjusted p < 0.05 and |fold-change|>1.5, five RBPs (EIF1AY, RPS4Y1, DDX3Y, RNASE2, and CSDC2) were found in heart failure LV myocardium specimens in comparison to nonfailing controls." (PMID 36313471, 2022).
pancreatic cancer (2 papers, 2016 to 2025). "During the in-depth exploration of the pancreatic cancer microenvironment, four distinct cell populations were successfully identified and isolated, namely C0 RPS4Y1+ tumor cells, C1 LYZ+ tumor cells, C2 CPE+ tumor cells, and C3 MKl67+ tumor cells." (PMID 40230840, 2025). "The CNV score and taurine metabolism score highlighted the significant role of RPS4Y1+ tumor cells within the immunosuppressive microenvironment of pancreatic cancer." (PMID 40230840, 2025). "Given the unique taurine imbalance characteristics of C0 RPS4Y1+ tumor cells within the pancreatic cancer tumor microenvironment, we further scrutinized the intercellular communication status of this subpopulation." (PMID 40230840, 2025). "The intimate communication between fibroblasts and C0 RPS4Y1+ tumor cells may impinge on the “hard cancer” characteristics of pancreatic cancer via multiple pathways." (PMID 40230840, 2025).
Parkinson disease (2 papers, 2019 to 2021). A progressive degenerative disorder of the central nervous system characterized by loss of dopamine producing neurons in the substantia nigra and the presence of Lewy bodies in the substantia nigra and locus coeruleus. "DLG1 and RPS4Y1 have been reported as distinct candidate genes or risk factors for early Parkinson's disease by analysis of gene expression in whole blood." (PMID 31487305, 2019).
asthma (1 paper, 2025). "RPS4X and RPS4Y1 are X and Y-chromosome-linked genes coding ribosomal subunits previously associated with inflammation, airway remodelling and asthma medication efficacy." (PMID 40649992, 2025). "We have identified that RPS4Y1 regulates hallmark asthma-relevant pathological processes of inflammation, cell adhesion and migration, and mediation of the extracellular matrix." (PMID 40649992, 2025). "Some studies have identified an association between RPS4Y1 expression and asthma through various immune cells." (PMID 40649992, 2025). "Furthermore, we have identified novel functional effects of RPS4Y1 that directly relate to the hallmark features of asthma–inflammation and fibrosis." (PMID 40649992, 2025). "Therefore, the pathologically relevant functions of RPS4Y1 may contribute to the complex sexually dimorphic pattern of asthma susceptibility and progression." (PMID 40649992, 2025). "Furthermore, we show that RPS4Y1 mediates the expression of integrin subunits α4 and β8, which are associated with tenascin-C, increasing cell adhesion and migration, which are known to contribute to worse asthma outcomes." (PMID 40649992, 2025). "Therefore, dysregulation of SPDEF expression by RPS4Y1 may predispose male children to asthma development." (PMID 40649992, 2025). "Further, RPS4Y1 modulates the response of patients to oral corticosteroids (an essential treatment for asthma patients), modulation of the inflammatory response and fibrotic processes." (PMID 40649992, 2025). "The heatmaps presenting the expression of RPS4X and RPS4Y1 indicate that their expression changes with asthma in a cell-specific pattern." (PMID 40649992, 2025). "Our findings provide a strong foundation for future studies to further elucidate and validate the role of RPS4Y1 in the context of asthma." (PMID 40649992, 2025). "We identify a complex regulatory function of RPS4Y1 for three pertinent proteins in the context of asthma: fibronectin, tenascin-C (TNC) and collagen 4α1." (PMID 40649992, 2025). "This study aims to explore and characterise the regulatory role of RPS4Y1 for inflammatory and fibrotic processes relevant to asthma." (PMID 40649992, 2025). "The functional contribution of RPS4Y1 to the clinical outcomes of patients with asthma is confirmed through our correlation of GSVA enrichment scores and lung function outcomes." (PMID 40649992, 2025). "Further, RPS4Y1 expression was lower in male asthma patients than in male controls, while RPS4X expression did not change in asthma for either sex." (PMID 40649992, 2025). "This study shows that RPS4Y1 expression is cell-specific and different to its X-linked counterpart, RPS4X, in asthma." (PMID 40649992, 2025). "The apparent selectivity of RPS4Y1 to regulate the translation of protein extends to extracellular matrix proteins that are dysregulated in asthma, which we hypothesise promotes altered fibrotic processes of cell adhesion and migration." (PMID 40649992, 2025). "RPS4Y1 has been less widely studied but has been identified to be dysregulated in asthma." (PMID 40649992, 2025). "As such, RPS4Y1 expression demonstrates cell-specific responsiveness in asthma patients." (PMID 40649992, 2025). "Notably, these processes are hallmark features of asthma, highlighting a potential contribution of RPS4Y1 to asthma pathology." (PMID 40649992, 2025). "Genes upregulated in RPS4Y1 KOs cells at baseline demonstrated a positive correlation with the severity of airflow obstruction as reflected by FEV1% predicted only in male patients with asthma." (PMID 40649992, 2025). "Altogether, these data highlight that the RPS4Y1 function is altered in asthma and may contribute to unique gene expression profiles between males and females." (PMID 40649992, 2025). "Furthermore, an RPS4Y1-centric gene signature correlates with clinical lung function measurements, specifically in adult male asthma patients." (PMID 40649992, 2025).
asthma (continued). "As females do not express RPS4Y1, its pathologically relevant functions may contribute to sex differences in asthma susceptibility and progression." (PMID 40649992, 2025). "Nonetheless, these data highlight a strong relationship between RPS4Y1 and ECM proteins that are prominent in asthma, indicating a role for RPS4Y1 in asthma progression." (PMID 40649992, 2025). "Using CRISPR-Cas9 knockout cellular models for RPS4Y1 and RPS4X, we characterised the function of RPS4Y1 in the context of the asthma-relevant processes, inflammation and fibrosis." (PMID 40649992, 2025). "We also establish that RPS4Y1 regulates a specific gene signature that is only dysregulated in males with asthma, indicating that the imbalance of RPS4Y1 and RPS4X expression between males and females may contribute to sex differences in asthma." (PMID 40649992, 2025). "However, as RPS4X expression does not change in asthma, reduced expression of RPS4Y1 has functional consequences as recognised through FEV1% predicted measurement in asthma." (PMID 40649992, 2025). "As such, we investigated how asthma-associated ECM proteins fibronectin (FN1), tenascin-C (TNC) and collagen 4α1 (COL4A1) are altered at a transcriptional and protein level in the absence of RPS4Y1." (PMID 40649992, 2025). "We observed that genes upregulated when RPS4Y1 is knocked out do not correlate with any change in FEV1% predicted in healthy male and female patients or female asthma patients." (PMID 40649992, 2025). "Finally, we confirmed in bronchial biopsies that RPS4Y1 is downregulated in asthmatic males versus males without asthma, but RPS4X demonstrated similar expression in males and females with asthma compared to healthy controls." (PMID 40649992, 2025).
epilepsy (1 paper, 2025). A brain disorder characterized by episodes of abnormally increased neuronal discharge resulting in transient episodes of sensory or motor neurological dysfunction, or psychic dysfunction. "RNA-seq analysis of the iPSCs revealed that genes such as TTTY14, TBL1Y, MEG8, MEG9, BCORP1, and RPS4Y1 are not directly related to epilepsy." (PMID 40600194, 2025).
esophageal squamous cell carcinoma (1 paper, 2025). Esophageal squamous cell carcinoma (ESCC) is a type of esophageal carcinoma (EC) that can affect any part of the esophagus, but is usually located in the upper or middle third. "Although direct evidence linking RPS4Y1 to IBD is lacking, studies have shown its association with immune infiltration in idiopathic pulmonary fibrosis, multiple sclerosis, and esophageal squamous cell carcinoma." (PMID 40636118, 2025).
hemophilia (1 paper, 2021). Hemophilia is a genetic disorder characterized by spontaneous hemorrhage or prolonged bleeding due to factor VIII or IX deficiency. "The availability of the RPS4Y1-targeting monoclonal antibody should facilitate the development of novel methods for the reliable isolation of male fetal cells from the maternal blood and their future use for non-invasive prenatal diagnosis of X-linked inherited disease such as hemophilia." (PMID 33670450, 2021).
lung carcinoma (1 paper, 2008). "Furthermore, seven of these genes (not including RPS4Y1) were implicated and studied in various cancers, but only HMGA2 was recently reported to be over expressed in lung cancer and inversely associated with survival." (PMID 19025616, 2008).
Turner syndrome (1 paper, 2024). Turner syndrome is a chromosomal disorder associated with the complete or partial absence of an X chromosome. "As expected, we found no expression of Y-linked genes in the Y depleted ARPE-19 clone 3, with the most downregulated gene being the Ribosomal Protein S4 Y-Linked 1 (RPS4Y1), whose haploinsufficiency plays a role in the Y negative Turner Syndrome." (PMID 38291538, 2024).
cancer (7 papers, 2008 to 2025). A tumor composed of atypical neoplastic, often pleomorphic cells that invade other tissues. "In contrast, AML1 exhibited higher expression levels of genes encoding ribosomal proteins, including RPS26 and RPS4Y1, which may promote cancer metastasis and spread, and their presence is correlated with increased disease aggressiveness and poor clinical outcomes." (PMID 37615858, 2024). "RPS4Y1 and DDX3Y have been among downregulated genes in 12 cancers in a recent whole transcriptome analysis." (PMID 36119500, 2022). "There was a very high-degree of commonality across all the models, with three Y-chromosome genes selected across all 17 cancers (ZFY, EIF1AY, and DDX3Y), RPS4Y1 (also on the Y-chromosome) selected across 15 of 17 cancers, and XIST (on the X-chromosome) selected across 14 of 17 cancers." (PMID 26755347, 2016).
tumor (4 papers, 2016 to 2025). "We compared the functions of CD8+ T cells between these two groups in order to better determine whether the presence of RPS4Y1+ tumor cells is associated with impaired T cell responses." (PMID 40230840, 2025). "To analyze whether C0 RPS4Y1+ tumor cells could affect the anti-tumor immune effect, we first developed a risk scoring system based on the top 100 marker genes of C0 RPS4Y1+ tumor cells." (PMID 40230840, 2025). "In the investigation of cell-cell communication, it was discovered that C0 RPS4Y1+ tumor cells had the most frequent communication with fibroblasts." (PMID 40230840, 2025). "The findings revealed that C0 RPS4Y1+ tumor cells exhibited the highest malignancy score, whereas S.Score and G2M.Score were comparatively lower for this cluster." (PMID 40230840, 2025). "A comprehensive and thorough investigation of the interaction mechanisms between C0 RPS4Y1+ tumor cells and other cells is required." (PMID 40230840, 2025). "Subsequently, we examined the ligand-receptor pairs of these signals, noting that ligands such as MIF, MDK, and APP are highly expressed on C0 RPS4Y1+ tumor cells and are instrumental in mediating communication with other tumor microenvironments." (PMID 40230840, 2025). "Then, the single-cell samples were stratified according to the proportion of C0 RPS4Y1+ tumor cells to create a “high C0 score” group and a “low C0 score” group." (PMID 40230840, 2025). "It is worthy of note that C0 RPS4Y1+ tumor cells exhibited the unique characteristics of a low taurine score and a high CNV index." (PMID 40230840, 2025). "A high CNV index reflects a substantial augmentation in the genomic instability of C0 RPS4Y1+ tumor cells." (PMID 40230840, 2025). "Within the CDH1-dominated signaling pathway, the four tumor subpopulation cells interacted with each other, with C0 RPS4Y1+ tumor cells primarily being influenced, hinting at the evolutionary dynamics and crosstalk among tumor cells." (PMID 40230840, 2025). "C0 RPS4Y1+ tumor cells mainly corresponded to the M3 and M2 modules, C1 LYZ+ tumor cells mainly corresponded to the M4 module, C2 CPE+ tumor cells mainly corresponded to the M1 module, and the specificity of C3 MKl67+ tumor cells was not very significant." (PMID 40230840, 2025). "Among them, C0 RPS4Y1+ tumor cells exhibited the highest malignancy score, while their S.Score and G2M.Score were comparatively low, intimating unique attributes of this cell population within the cell cycle progression." (PMID 40230840, 2025). "In the tumor microenvironment, particularly in a highly malignant milieu such as that of C0 RPS4Y1+ tumor cells, the taurine metabolic pathway may be inhibited." (PMID 40230840, 2025). "Conversely, C0 RPS4Y1+ tumor cells transmitted more signals to CD8+ T cells." (PMID 40230840, 2025). "FLK4, BACH1, and GMEB2 were important regulators of C0 RPS4Y1+ tumor cells." (PMID 40230840, 2025). "We observed cellular crosstalk centered around C0 RPS4Y1+ tumor cells." (PMID 40230840, 2025). "The signal communication between C0 RPS4Y1+ tumor cells and fibroblasts may regulate the activation and proliferation of fibroblasts, further propelling the production of extracellular matrix." (PMID 40230840, 2025). "Through cell-communication analysis, the crosstalk among fibroblasts, CD8+ T cells, and RPS4Y1+ tumor cells was identified, offering novel insights into immunotherapy strategies, which was strengthened by the co-localization analysis of spatial transcriptomics." (PMID 40230840, 2025). "Fibroblasts emerged as the predominant source of cellular signals to C0 RPS4Y1+ tumor cells, suggesting that fibroblasts may play a pivotal role in mediating PC taurine imbalance and tumor immunity." (PMID 40230840, 2025). "In the present study, four distinct tumor cell subsets, namely RPS4Y1+ tumor cells, LYZ+ tumor cells, CPE+ tumor cells, and MKI67+ tumor cells, were identified for the first time." (PMID 40230840, 2025).
tumor (continued). "We therefore tried to separate these effects, starting by testing for non-tumor patient characteristics like age and sex: higher XIST expression was observed in females, and higher RPS4Y1 expression in males." (PMID 35158950, 2022). "As in tumors, the genes ZFY, RPS4Y1, DDX3Y were selected in all of the tissue types for the male vs. tumor analyses in normal samples, and RPS4Y1 was selected in the majority of tissue types." (PMID 26755347, 2016).
immune disorders (1 paper, 2024). "Additionally, phagosomes were implicated in certain immune disorders, with RPS4Y1, RPS10, SRRM1, and PNN target genes playing roles in the NOD-like receptor signaling pathway." (PMID 38770048, 2024).
RPS4Y1 also shares sentences with these, for which no sentence is quoted: autoimmune disease (2 papers); COVID-19 (2); idiopathic dilated cardiomyopathy (2); Alzheimer disease (1); autism (1); congenital heart disease (1); developmental delays (1); diabetes (1); gastric cancer (1); hepatoma (1); hypothyroidism (1); idiopathic pulmonary fibrosis (1); leukemia (1); liver cancer (1); multiple sclerosis (1); neurological diseases (1); psychiatric disorder (1); X-linked inherited disease (1).